PRR12 (proline rich 12)
Description:
May play a role in the regulation of cohesin complex loading onto chromatin, probably acting in coordination with NIPBL and MAU2.
Synonyms: KIAA1205; NOC
Tractability: PROTAC: ubiquitination databases record sites on it; its protein half-life has been measured.
Gene: Protein-coding gene on chromosome 19 (49,591,182 to 49,626,439, forward strand). Ensembl gene ENSG00000126464.
Subcellular location: Nucleus; Postsynaptic density; Synapse, synaptosome
Subcellular location (Human Protein Atlas): Cytosol
Gene Ontology:
Molecular function: protein binding
Biological process: intracellular protein localization
Cellular component: nucleus; postsynaptic density; synapse
Genetic constraint (gnomAD): Loss-of-function variants: 11 observed, 100.95 expected, observed/expected ratio (o/e) 0.11, 90% interval 0.068 to 0.18. The synonymous counts are far from expectation, so gnomAD's model fits this gene poorly and the ratio says little. Missense variants: 2,684 observed, 2,541.2 expected, observed/expected ratio (o/e) 1.06, 90% interval 1.02 to 1.09. Synonymous variants: 1,558 observed, 1,173.3 expected, observed/expected ratio (o/e) 1.33, 90% interval 1.27 to 1.38.
Gene-disease validity (ClinGen):
ClinGen rates the evidence that PRR12 causes each of these diseases.
neuroocular syndrome (autosomal dominant): Definitive.
Homologues: Orthologues: chimpanzee PRR12 (99% identical), macaque PRR12 (99% identical), mouse Prr12 (93% identical), rat Prr12 (93% identical), dog PRR12 (92% identical), guinea pig PRR12 (55% identical), zebrafish prr12b (49% identical), tropical clawed frog prr12 (48% identical), zebrafish prr12a (48% identical). Paralogues in human: QSER1 (28% identical).
Diseases named in the same sentence as PRR12 in open-access papers:
PRR12 is named in the same sentence as 12 diseases in open-access papers, as found by Europe PMC text mining. Sharing a sentence is not in itself a finding about the gene and the disease. The quoted sentences say what the papers report.
Intellectual disability (7 papers, 2020 to 2025). "Individuals carriers of high impact variants on PRR12 had neurodevelopmental disorders, for example, autism, intellectual disability, and attention-deficit/hyperactivity disorder (ADHD)." (PMID 35057575, 2022). "PRR12 encodes a proline-rich protein nuclear factor associated to neurodevelopmental disorders and intellectual disability." (PMID 35368691, 2022). "Translocations involving PRR12 have linked PRR12 to the development of intellectual disability, suggesting a role in neuronal development." (PMID 32439918, 2020). "Patients with PRR12 gene presented with intellectual disability (ID), neuropsychiatric disorders, some congenital anomalies, and with or without eye abnormalities." (PMID 38798311, 2024). "Cordova-Fletes and colleagues reported on a de novo balanced translocation disrupting the PRR12 gene in a girl affected by intellectual disability and neuropsychiatric alterations." (PMID 34768579, 2021).
glioma (2 papers, 2020 to 2024). A benign or malignant brain and spinal cord tumor that arises from glial cells (astrocytes, oligodendrocytes, ependymal cells). "Furthermore, recent works have highlighted PRR12 contribution in gliomas malignancy through control of cell survival and metastatic migration via the RAD21/MIR4697HG-miR7665p/PRR12 axis." (PMID 38674426, 2024).
neuro-ocular syndrome (2 papers, 2024). "Patients with neuroocular syndrome are rare, and further exploration is needed to understand the reason for neurodevelopmental abnormalities caused by PRR12 variants." (PMID 38798311, 2024). "Haploinsufficiency of the PRR12 gene is implicated in a human neuro-ocular syndrome." (PMID 38674426, 2024). "The variants in the PRR12 gene were reported to be related to neuroocular syndrome." (PMID 38798311, 2024).
coloboma (1 paper, 2024). An abnormality in which a part of a structure in one or both eyes is missing. "As PRR12 variants have been associated with visual system developmental defects involving coloboma, microphtalmia and anophtalmia, we decided to conduct an in-depth analysis of prr12 distribution in the embryonic eye at 72 hpf, when retinal lamination is completed and the retina is functional." (PMID 38674426, 2024).
PRR12 also shares sentences with these, for which no sentence is quoted: neurodevelopmental disorder (3 papers); developmental delay (2); autism (1); diabetes (1); iris coloboma (1); microcephaly (1); Obesity (1); scoliosis (1).